TNF (tumor necrosis factor)
Diseases named in the same sentence as TNF in open-access papers (continued):
Sharing a sentence is not in itself a finding about the gene and the disease.
Sepsis (continued). "In another study, LPS was shown to downregulate Pparg expression in macrophages and in the liver of rats during sepsis via an increase in TNF release." (PMID 37505851, 2023). "Innate and adaptive immunity associated miRNA regulates the TNF and the TLR/NF-kB signaling pathway in sepsis." (PMID 36902469, 2023). "In this study, SJS can improve the 7-day survival rate of sepsis mice, inhibit the release of inflammatory cytokines IL-1β, IL-6, TNF-α, and increase the production of IL-10 in the early stage." (PMID 37062835, 2023). "In sepsis patients’ whole blood assays, the blockers significantly decreased supernatant concentrations of TNF and IL-6 in response to added heat-killed E. coli and S. aureus, and of IL-1β in response to S. aureus." (PMID 37869001, 2023). "Over the next 18 years (1998–2016), the focus gradually shifted to intervention effect, tumor necrosis factor-alpha, clinical trial, encephalitis, reperfusion injury, sepsis, anti-inflammatory activity, mechanism of action, innate immunity, and astrocytes." (PMID 38029105, 2023). "On the other hand, in murine studies of the cecal ligation and puncture (CLP) sepsis model, the overexpression of miR-181b was shown to attenuate neuroinflammation through the downregulation of NF-ΚB, IL-1β, and TNFα." (PMID 37569277, 2023). "Aging leads to elevated baseline TNF-α production by circulating leukocytes and impaired responses to TLR2 and TLR4 agonists, potentially rendering older adults more susceptible to sepsis." (PMID 38001481, 2023). "TNF-α is the most studied pro-inflammatory cytokine in sepsis due to its deterministic role in the release of other cytokines." (PMID 37626822, 2023). "TNF-α involve in the pathogenesis of sepsis and inhibited it will have significant therapeutic effects." (PMID 37494665, 2023). "ApoE23 treatment dramatically decreased plasma TNF-α and IL-6 levels at the three time points compared to those in the sepsis group." (PMID 37533741, 2023). "CLP-induced experimental sepsis resulted in a significant upregulation in the expression levels of TNF-α, IL-1β, IL-6, IL-10, ROS and MDA." (PMID 36608000, 2023). "During liver failure in an experimental model of sepsis in rats, glucose metabolism is disturbed, transaminase activity increases, and levels of IL-1β, TNF-α, and IL-6 increase." (PMID 38203627, 2023). "For example, in sepsis, cytokines such as IL-6, TNF-α, IL-1β, and CXCL8 increase antibody production, vascular permeability, and neutrophil recruitment." (PMID 37600769, 2023). "In agreement, another study reported an inverse relationship between the plasma levels of IL-6, MMP-8 and CXCL9 (indicative of systemic inflammation) and the TNF production capacity of whole blood obtained from patients with sepsis." (PMID 37415223, 2023). "At least some of the pathobiology of sepsis is driven by necroptosis, usually initiated in a TNF-α-dependent manner, which initiates downstream signaling cascades driving the production of proinflammatory cytokines." (PMID 36765040, 2023). "Instead, infusion of tempol directly into the renal artery prevented sepsis‐induced upregulation of TNF‐α in cortical tissue and uncoupling of eNOS in medullary tissue." (PMID 37548350, 2023). "Tumor necrosis factor-α (TNF-α) was a key regulator of innate immunity related to sepsis-induced acute lung injury." (PMID 36817458, 2023). "LD patients show profound alterations in TNF-α secretion after LPS stimulation, the degree of alteration being related to disease severity as it has been described in sepsis." (PMID 37965258, 2023). "In this study, a total of 33 putative targets were obtained by merging the SIN-targets and sepsis-related targets, and there were 3 genes with a higher degree: TNF-α, IL-6, and IL-1β." (PMID 37388447, 2023). "While IL-6, PIGF, and CRP were also significantly elevated in post-Sepsis patients compared to controls, the observed differences in TNFα, Tie-2, Flt-1, IL-7 and bFGF were unique to the post-COVID group." (PMID 36844209, 2023).
Sepsis (continued). "In this article, sepsis dramatically increased the levels of the inflammatory cytokines IL-1β, IL-6, and TNF-α, although this rise was reduced following PTP treatment." (PMID 37361224, 2023). "It was demonstrated that SIRT1 reduces H3K16 acetylation and inhibits TNF-α transcription during sepsis-induced inflammation by targeting the TNF-α promoter." (PMID 36774341, 2023). "LL-37 released from neutrophils suppresses sepsis in mice and inhibits IL-1β and TNF-α production in macrophages by suppressing LPS-stimulated CD14/TLR4 activation and the subsequent NF-κB signalling pathway and activation of P2X7 by ATP from dead/dying cells." (PMID 37569540, 2023). "Among the molecular variables, IL-1Ra, IL-17A, CCL19, CX3CL1 and TNF were significantly higher in septic patients compared to the infection non-sepsis group." (PMID 37691028, 2023). "As seen for HLA-DR quantitation, no receiver operating characteristic (ROC) curve analysis has been performed to define a TNF-α threshold for sepsis IP." (PMID 36825018, 2023). "In accord, TNF‐α expression is increased in the glomeruli and proximal convoluted tubules, mainly located within the renal cortex, in rodent models of sepsis." (PMID 37548350, 2023). "We also performed ELISA to assay the expression of inflammatory cytokines, and results revealed that the concentrations of TNF‐α, IL‐1β, and IL‐6 were notably increased in the sepsis cell model (p < .001)." (PMID 37647440, 2023). "Numerous anti-inflammatory immunomodulatory treatments have been used to combat the proinflammatory phase of sepsis; however, these immunomodulatory agents (TNF-α, IL-1β, toll-like receptor-4, etc.)have failed in clinical trials." (PMID 36816800, 2023). "Sepsis activates microglia and promotes the production of pro-inflammatory factors (TNF-α), which increases the intrinsic excitability and synaptic transmission of cerebellar Purkinje cells and ultimately impairs motor learning and behavior." (PMID 38027963, 2023). "Levels of cytokines (such as interleukin-8 [IL-8], tumor necrosis factor -α [TNF-α], IL-10, and IL-6) and endotoxins are often elevated in patients with sepsis." (PMID 36650427, 2023). "The administration of GAPDH exerts an anti-inflammatory effect by reducing tumor necrosis factor alpha (TNFα) levels in a mouse model of sepsis." (PMID 36818560, 2023). "In the sepsis group (control), TNFα lung concentration was significantly higher (p<0.05) compared to the sham group, while the difference between the sepsis and vehicle groups was minimal." (PMID 37675176, 2023). "During sepsis, pro-inflammatory cytokines such as TNF-α and IL-1β are released by sentinel innate immune cells at the infection site and activated by pathogen-associated molecular pattern (PAMPS) and damage-associated molecular pattern (DAMPS)." (PMID 37575989, 2023). "According to the reviewed research articles, MIP-based biosensors can be applied for inflammation and sepsis biomarkers, such as human serum albumin, C-reactive protein, serum amyloid A, tumor necrosis factor-alpha (TNF-α), procalcitonin, IL-6, and IL-1β." (PMID 37366985, 2023). "Platelets have shown a protective role in sepsis through the down regulation of macrophage-dependent proinflammatory cytokines (TNF-α and IL-6)." (PMID 37486928, 2023). "Despite potential validity and utility of markers for sepsis IP, such as human leukocyte antigen-DR (HLA-DR), tumor necrosis factor (TNF)-α, or absolute lymphocyte counts (ALC), the CARS paradigm faces 2 fundamental challenges." (PMID 36825018, 2023). "EA and Acu-exo reduced the W/D and lung tissue damage in sepsis mice, down-regulated the expression of serum inflammatory cytokines TNF-α and IL-6, and increased the survival rate of sepsis mice." (PMID 37635258, 2023). "It has been considered as promising therapeutic target for treating sepsis and MI, and anti-TNF-α immunotherapy has been developed for treating sepsis." (PMID 37388447, 2023).
Sepsis (continued). "Ticagrelor treatment resulted in lower tissue levels of TNFα in the lung compared to the sepsis and vehicle groups." (PMID 37675176, 2023). "Administering IL-10 within hours of the onset of sepsis suppresses TNF-α secretion and prolongs the therapeutic potential of rescue surgery." (PMID 37626822, 2023). "The pathogenesis of sepsis is accompanied by the overactivation of various inflammatory factors, including IL‐1β, TNF‐α, and IL‐10." (PMID 37382273, 2023). "One of the most significant biomarkers of sepsis is the proinflammatory cytokines IL-6 and TNF-α, which are closely related to patient outcomes." (PMID 37293234, 2023). "In sepsis mice, the production of liver TNF-α and IL-6 was also decreased by treatment with BAM15 particles but not BAM15, while the liver IL-10 level was not affected by all treatments." (PMID 38140036, 2023). "Frustratingly, over 100 published clinical trials in sepsis targeting microbial factors, cytokines (including anti-TNF-alpha and anti-IL-1 beta monoclonal antibodies), and blood coagulation regulators have thus far failed." (PMID 37638006, 2023). "Endothelial progenitor cell-derived extracellular vesicles containing miR-93-5p exert a protective effect on endothelial cells by regulating the (K)-specific demethylase 6B (KDM6B lysine)/H3K27me3/TNF-α axis in sepsis-induced acute kidney injury." (PMID 36774341, 2023). "Our network pharmacology analysis revealed SJS treated sepsis through multiple pathways and multiple targets, including NF-kB pathway, TNF signaling pathway and IL-17 signaling pathway, which is reported to be closely related to the inflammation and immunity." (PMID 37062835, 2023). "In an LPS-induced sepsis mouse model, pulmonary endothelial heparanase was activated in a TNF-α dependent manner." (PMID 36865384, 2023). "Inflammatory cytokines such as IL-1, IL-6, IL-18 and TNF-α are critically involved in the pathogenesis of sepsis." (PMID 37494665, 2023). "In LPS‐induced mice sepsis, pretreatment of 50 mg/kg CA greatly promoted the survival rate of septic mice and reduced the serum concentrations of IL‐1β and tumor necrosis factor (TNF)‐α." (PMID 37090118, 2023). "COS has also been shown to reduce systemic inflammatory responses, as indicated by serum levels of TNF-α and IL-1β and damage to the liver, kidney, and lung in a mouse model of LPS-induced sepsis." (PMID 37476483, 2023). "In sepsis, TNF-α and other cytokines were related to the reduction in myocardial contractility after in vitro exposure for ≥10 min." (PMID 37288294, 2023). "From our data, it is very obvious that both IL-6 and TNF-α levels were significantly elevated in Peli1 global knockout mice after sepsis compared to the other sepsis groups." (PMID 37296648, 2023). "In patients with severe sepsis or septic shock, high doses of the murine anti-TNF-α antibody, CB0006, were well tolerated, with a tendency to improve survival in the subgroup with high plasma TNF-α concentrations." (PMID 38114466, 2023). "Some studies have found that after continuous venous hemofiltration for severe sepsis, the secretion level of TNF-α was significantly reduced in patients." (PMID 38066783, 2023). "Using bioinformatics analysis and a drug repositioning strategy, we predicted a set of potential drug candidates for sepsis and validated the effectiveness of one of these drugs in vitro and in vivo models of TNF-α-induced necroptosis." (PMID 36765040, 2023). "To investigate the role of TNF-α in sepsis, we measured the levels of this pro-inflammatory cytokine in the serum of mice using ELISA." (PMID 37465664, 2023). "Meanwhile, the cytokine levels in the plasma of rat including IL‐17A, TNF, and IL‐6, the critical factors for the disorder of immune system and high mortality in sepsis model, were measured by flow cytometry analysis." (PMID 38023725, 2023).
Sepsis (continued). "In a TLR4-induced sepsis animal model, treatment with S. thermophiles alleviates intestinal injury and decreases the serum levels of inflammatory cytokines (IL-6 and TNF-α)." (PMID 36838243, 2023). "In sepsis, these cytokines (IL-1α, IL-1β, IL-6, and TNFα) can be released in the blood and cross the BBB through their respective transporters." (PMID 37569277, 2023). "Reports from as early as 1993 revealed increased IL-1β abundance in plasma from 10 newborns with clinical sepsis, in addition to increased TNF and IL-6, as compared to 22 healthy controls." (PMID 36769133, 2023). "Our results revealed that LGG promoted the recovery of the colon epithelial structure under sepsis and a TNF-α treatment." (PMID 36771378, 2023). "Alternatively, the inhibition of cytokine functions has been largely developed using anti-interleukin or anti-TNF monoclonal antibodies in the treatment of sepsis or chronic inflammation." (PMID 37298597, 2023). "Zhang and Miyazawa reported that LF neutralizes endotoxins in cases of septicemia and is possibly a curative treatment for septicemia by decreasing TNF-α concentration." (PMID 36495415, 2023). "In this study, we found that betaine given by ip injection in the sepsis group decreased the levels of pro-inflammatory cytokines (TNF-α, CRP, IL 1-β, IL-6) and oxidative stress biomarkers (MDA, LA) and increased PaO2." (PMID 37970921, 2023). "Treatment with curcumin led to the regulation of protein expression of IKKβ, IκBα, p-NF-κB, TNF-α, IL-1β, and IL-18 stimulated by sepsis." (PMID 36756300, 2023). "In sepsis, cytokines, such as IL-lβ, TNF-α, bacterial endotoxin, and lipopolysaccharide, can increase PAI-1 synthesis and secretion in endothelial cells, inhibiting the fibrinolytic system." (PMID 37159591, 2023). "The plasma concentration of TNF‐α increased from 0.9 ± 0.4 to 7.5 ± 2.4 ng mL−1 after 4 h of sepsis in the vehicle‐treated group, prior to returning toward premorbid levels by 24 h of sepsis (0.9 ± 0.2 ng mL−1)." (PMID 37548350, 2023). "TNF-α is the earliest inflammatory factor synthesized during the occurrence and development of sepsis, and also one of the initiating factors of sepsis." (PMID 37753078, 2023). "Another study suggested that MALAT1 depletion is responsible for the sepsis inflammatory response by inhibiting the expression of IL-6 and TNF-α and the NF-κB signaling pathway by upregulating miR-150-5p." (PMID 37109540, 2023). "This supports bacterial-sepsis-induced T cell exhaustion leading to an evident loss of inflammatory cytokine IFN-γ and TNF-α production from T cells following stimulation." (PMID 36979757, 2023). "In the cecal ligation and puncture (CLP)-induced sepsis model, the number of CX3CR1+CCR2-CD64+CRMs begins to decrease from the first day of sepsis, which is associated with TNF-α and IL-6 signaling and leukocyte infiltration." (PMID 38027963, 2023). "Numerous studies have also shown that excessive release of pro-inflammatory cytokines, such as IL-1β, IL-6 and TNF-α, triggers pathophysiological abnormalities in sepsis and plays an important role in septic lung injury." (PMID 36737780, 2023). "The inflammatory cytokines such as tumor necrosis factor-α (TNF-α), interleukin 1, and the complement system in sepsis models downregulate the anticoagulant pathways in sepsis." (PMID 36878489, 2023). "T lymphoneia associated with concomitantly elevated TNF and IL-6 in the serum at 12 hpi in LPS sepsis or CLP sepsis, among other pro-inflammatory cytokines and chemokines (PICC)." (PMID 37332010, 2023). "The ratio of DCs expressing MHC-II, CD86, and CD80, the mRNAs level of dendritic cells expressing TNF-α and IL-12, and the level of DC-mediated T-cell proliferation were all decreased, both in vivo and in vitro during sepsis, when PINK1 was knocked out." (PMID 36809929, 2023). "NRF2 inhibits pro-inflammatory signaling pathways such as TNF-α signaling and is involved in regulating the innate immune response during sepsis." (PMID 37007526, 2023).
Sepsis (continued). "In sepsis, TNF‐α production within the kidneys is mediated by the infiltration of innate immune cells including neutrophils." (PMID 37548350, 2023). "The plasma TNF-α level in the sepsis group increased dramatically at the 1 h time point and then continued to decrease at 3 h and 24 h compared to the sepsis control group (P < 0.01)." (PMID 37533741, 2023). "On the other hand, injection of LPS in mice induces a strong, short-term increase of plasma proinflammatory cytokines (e.g., TNF-α, IL-1β and IL-6), in comparison to the lower and progressive cytokine increase in human sepsis [,48]." (PMID 37456011, 2023). "In this investigation, the sepsis group considerably outperformed the sham group in terms of blood levels of TNF-, TNF- receptor, and IL-6 (P<0.05)." (PMID 36937479, 2023). "It was shown that δV1-1 reduced TNF-α-mediated hyperpermeability as well as neutrophils adhesion and migration across HBMVECs in sepsis-induced vascular damage." (PMID 37974282, 2023). "In vivo, MAF (20 mg/kg) markedly protected the sepsis mice and reduced the serum TNF‐α and IL‐6 levels." (PMID 38455195, 2023). "Previous reports indicated that the LPS-induced release of HMGB1 was associated with sepsis and that HMGB1 is an inflammatory mediator that can increase the levels of TNF-α, IL-6 and IL-1β." (PMID 38026444, 2023). "We observed a significant reduction in IL-1-β, IL-6, and TNF-α pro-inflammatory cytokines with betaine treatment in sepsis-induced rats, in line with the studies in the literature." (PMID 37970921, 2023). "The study looked at the role of P2Y12 in controlling sepsis-induced increases in plasma cytokine levels (tumor necrosis factor-, interleukin-6, and macrophage inflammatory protein-1β)." (PMID 37675176, 2023). "While only ELISpot revealed a relationship between LPS-induced TNF production over time, both assays revealed decreases in total and lymphocyte-adjusted IFNγ concentrations over the first 2 weeks following sepsis/critical illness." (PMID 37831231, 2023). "A study showed a lower TNF-α response to LPS in patients with sepsis or septic shock compared to less severe post-surgical patients." (PMID 37965258, 2023). "Then, we explored the inflammation responses during sepsis, where the serum levels of the inflammatory markers (IL-6 and TNF-α) were determined." (PMID 37512913, 2023). "It is well known that the TRIF-dependent pathway plays a key role in the pathogenesis of sepsis by mediating the production of TNF-α, IL-1, IFN-γ, and chemokines." (PMID 37465127, 2023). "We further analyzed the area under ROC curve of disease severity score (SOFA score, APACHE II score), peripheral blood AQP4, and inflammatory factors such as TNF‐α, IL‐6, and IL‐1β of sepsis along with SAE patients." (PMID 36922751, 2023). "Recently, antagonistic therapies anticytokine therapy targeting (tumor necrosis factor alpha [TNF-alpha], interleukin-1 [IL-1]) and anti-endotoxin strategies have been proposed as important therapeutic targets in sepsis." (PMID 38068931, 2023). "The current findings showed that FP-induced and PCP-pretreated sepsis mice resulted in lower TNF-α, IL-6, and IL-1β contents in plasma, downregulating expression of Treg cells in the spleen." (PMID 35694296, 2022). "ELISA results showed that the levels of inflammatory factors in the burn sepsis group were significantly higher than those in the other two groups and that IL-4, IL-6, and TNF-α continuously increased over time." (PMID 35280898, 2022). "The NF-κB signaling pathway is one of the key regulatory pathways of inflammatory response, and the changes in the expression of pathway-related genes such as CD14, MyD88, TNF-α, IL-1β, and IL-1R play an important role in the development of sepsis." (PMID 35186224, 2022). "Our results showed that the W/D weight ratio of lung tissue in rats with sepsis was significantly reduced by the neutralization of IL-17A, as well as the content of inflammatory factors, such as IL-6 and TNF-α." (PMID 36253831, 2022).